ZYG11B (zyg-11 family member B, cell cycle regulator)
Description:
Serves as substrate adapter subunit in the E3 ubiquitin ligase complex ZYG11B-CUL2-Elongin BC. Acts to target substrates bearing N-terminal degrons for proteasomal degradation with the first four residues of substrates being the key recognition elements. Prefers Nt-Gly but also has the capacity to recognize Nt-Ser, -Ala and -Cys. Involved in the clearance of proteolytic fragments generated by caspase cleavage during apoptosis since N-terminal glycine degrons are strongly enriched at caspase cleavage sites. Also important in the quality control of protein N-myristoylation in which N-terminal glycine degrons are conditionally exposed after a failure of N-myristoylation. In addition, plays a role in the amplification of cGAS to enhance innate immune response. Mechanistically, strengthens the processes of cGAS binding with dsDNA and assembling oligomers and also accelerates and stabilizes cGAS-DNA condensation, thereby enhancing production of antiviral IFNs and inflammatory cytokines.
Synonyms: FLJ13456; ZYG11
Tractability: Small molecule: a structure with a bound ligand is known. PROTAC: UniProt records ubiquitination sites on it; ubiquitination databases record sites on it; its protein half-life has been measured.
Gene: Protein-coding gene on chromosome 1 (52,726,447 to 52,827,336, forward strand). Ensembl gene ENSG00000162378.
Subcellular location: Cytoplasm
Subcellular location (Human Protein Atlas): Endoplasmic reticulum; Vesicles; Golgi apparatus
Gene Ontology:
Molecular function: protein binding
Biological process: positive regulation of proteasomal ubiquitin-dependent protein catabolic process; protein quality control for misfolded or incompletely synthesized proteins; proteasome-mediated ubiquitin-dependent protein catabolic process
Cellular component: Cul2-RING ubiquitin ligase complex; cytoplasm
Genetic constraint (gnomAD): Loss-of-function variants: 28 observed, 71.57 expected, observed/expected ratio (o/e) 0.39, 90% interval 0.29 to 0.54. The upper end of that interval is the gene's LOEUF score, 0.54, which puts it in group 2 of 6, group 1 being the genes least tolerant of losing a copy. Missense variants: 539 observed, 894.21 expected, observed/expected ratio (o/e) 0.6, 90% interval 0.56 to 0.65. Synonymous variants: 295 observed, 319.08 expected, observed/expected ratio (o/e) 0.92, 90% interval 0.84 to 1.02.
Homologues: Orthologues: dog ZYG11B (99% identical), macaque ZYG11B (99% identical), chimpanzee ZYG11B (99% identical), rabbit ZYG11B (99% identical), pig ZYG11B (98% identical), mouse Zyg11b (98% identical), rat Zyg11b (98% identical), guinea pig ZYG11B (98% identical), tropical clawed frog zyg11b (82% identical), zebrafish zyg11 (70% identical), zebrafish zyg11l (51% identical), Caenorhabditis elegans zyg-11 (28% identical). Paralogues in human: ZYG11A (62% identical), ZER1 (28% identical).
Diseases named in the same sentence as ZYG11B in open-access papers:
ZYG11B is named in the same sentence as 7 diseases in open-access papers, as found by Europe PMC text mining. Sharing a sentence is not in itself a finding about the gene and the disease. The quoted sentences say what the papers report.
respiratory infections (1 paper, 2024). "The S1 subunit post-transcriptionally promotes ZYG11B; therefore, vaccination in combination with SARS-CoV-2 infection may have a negative effect on pulmonary clearance by cilia and favor respiratory infections." (PMID 38674024, 2024).
infection (2 papers, 2021 to 2025). The state of being infected such as from the introduction of a foreign agent such as serum, vaccine, antigenic substance or organism. "If ORF10 depended on CRL2ZYG11B and/or CRL2ZER1 in order to promote infection, then ZYG11B/ZER1 KO cells would be expected to be resistant to SARS-CoV-2 infection." (PMID 33827988, 2021). "In addition, in the single-round infection model, we assessed the impact of ZYG11B on the protein and RNA levels of VP1 and another key structural protein, VP2." (PMID 40135890, 2025). "While most of ORF10, including the N terminus used to bind ZYG11B, is still retained in this strain, this nonetheless implies that the full open reading frame is not required for infection." (PMID 33827988, 2021). "While we cannot rule out that ORF10 may have other roles that are important for infection, any effect that ORF10 may have on ZYG11B is not relevant for SARS-CoV-2 infection in vitro." (PMID 33827988, 2021).
brain disorder (1 paper, 2020). A disease affecting the brain or part of the brain. "Four genes, ZYG11B, HECTD1, CAND1, and MYCBP2, ranked second, fourth, seventh and tenth, are all involved in protein ubiquitination, which has been implicated in neuronal function and brain disorders, including ASD." (PMID 33133139, 2020).
cancer (1 paper, 2025). A tumor composed of atypical neoplastic, often pleomorphic cells that invade other tissues. "We specifically confirmed the differential expressionof three Golgi-related genes (NIPAL1, PARP 10 and ZYG11B) between tumor andpara-cancer tissue." (PMID 41020586, 2025). "Uncontrolled cellcycle is a core feature of cancer development, and ZYG11B, as a regulator ofcell cycle, may play a role in the regulation of CRC cell proliferation andapoptosis." (PMID 41020586, 2025). "Furthermore, we analyzed our original chromatin accessibility data,and found that the DNA binding motifs of ELF1, JUND, and SPI1, which arepotential transcription factors of PARP10, NIPAL1 and ZYG11B in CRC tissues, arespecifically open in cancer tissues compared with adjacent tissues." (PMID 41020586, 2025).
ZYG11B also shares sentences with these, for which no sentence is quoted: enterovirus infections (1 paper); HIV-1 infection (1); tumor (1).